IL2 (interleukin 2)
Diseases named in the same sentence as IL2 in open-access papers (continued):
Sharing a sentence is not in itself a finding about the gene and the disease.
mesothelioma (20 papers, 1995 to 2025). A usually malignant and aggressive neoplasm of the mesothelium which is often associated with exposure to asbestos. "We have previously shown that intra-tumoral IL-2 combined with anti-CD40 antibody leads to AE17 mesothelioma tumor regression in young mice; this was associated with increased CTL activity." (PMID 30459812, 2018). "Human Vδ2 T cells were expanded from peripheral blood mononuclear cells using Tetrakis‐pivaloyloxymethyl 2‐(thiazole‐2‐ylamino) ethylidene‐1,1‐bisphosphonate (PTA) plus IL-2 for 13 days, before used to test for cytotoxicity against mesothelioma cell lines." (PMID 38077396, 2023). "It has been demonstrated that IL-2/CD40 agonist combination therapy results in NK cell infiltration into mesothelioma tumors." (PMID 34686187, 2021). "We have previously shown that local intra-tumoral administration of IL-2/anti-CD40 immunotherapy induces mesothelioma tumor regression in young (aged 2–3 months) female C57BL/6J mice; mediated primarily by neutrophils, CTLs and macrophages." (PMID 30459812, 2018). "Cetuximab inhibited intrathoracic mesothelioma growth in the mice, and this inhibition was markedly enhanced by IL-2 co-administration." (PMID 22922885, 2012). "A recent study evaluated various lymphocyte subpopulations after intra-tumoural administration of IL-2 in a murine model of mesothelioma." (PMID 19935800, 2009). "We conclude that IL-2 given intrapleurally is accompanied with acceptable toxicity and has anti-tumour activity against mesothelioma." (PMID 7577483, 1995). "Regardless, the clinical application of TIL therapy in mesothelioma faces substantial logistical challenges, including limited cell yields, complex expansion protocols, and reliance on IL-2 support, compounded by the low surgical eligibility rate of PM patients." (PMID 41463268, 2025). "For example, continuous intrapleural IL2 infusion has also been evaluated in clinical trials for the treatment of mesothelioma, and intrapleural cavity IL2 levels were measured to be 6000-fold higher than systemic leading to improvements in objective response rate and disease control rate." (PMID 35235346, 2022). "Taken together, we speculated that NFE2L3, a novel biomarker in malignant pleural mesothelioma, can promote Th2 cell differentiation via IL-2/STAT5/NLRP3 signaling pathway in mesothelioma and many other cancers." (PMID 35664314, 2022). "IL-2 for example is required to induce anti-mesothelioma activity by NK cells." (PMID 32391074, 2020). "Phase I clinical trials of mesothelioma treatment by oncolytic VV deleted of the TK gene and encoding IL-2 have demonstrated that this approach is not toxic but lacks therapeutic efficacy." (PMID 32995481, 2020). "Collectively, our data suggests that checkpoint blockade of inhibitory molecules may improve responses to IL-2/CD40 immunotherapy in elderly hosts with mesothelioma." (PMID 30560130, 2018). "IL-2 has been given into the pleura of patients with mesothelioma with some activity." (PMID 11875694, 2002). "Our study shows that aging programs development of a suppressive immune environment, which is reflected by DCs and T cells, and this may compromise generation of anti-tumor immune responses, influence mesothelioma progression and responses to IL-2/CD40 immunotherapy." (PMID 30560130, 2018). "The increased regulatory status of elderly DCs and T cells may not only affect tumor progression, but also the efficacy of anti-tumor immunotherapies, which is supported by our data showing that IL-2/CD40 immunotherapy is less effective in inducing mesothelioma regression in elderly mice." (PMID 30560130, 2018). "In view of the refractory nature of the disease IL-2 may be a treatment option for mesothelioma." (PMID 7577483, 1995). "We have previously shown that local IL-2/anti-CD40 immunotherapy can enhance anti-tumor T cell activity and intra-tumoral inflammation leading to resolution of mesothelioma tumors in young (aged 2–3 months) female C57BL/6J mice." (PMID 30459812, 2018).
mesothelioma (continued). "The aim of this study was to examine the influence of aging on DC and T cell function in healthy mice vs. mice with mesothelioma, and to examine responses to IL-2/CD40 immunotherapy in elderly and young mesothelioma-bearing mice." (PMID 30560130, 2018). "However, after local IL-2 and/or anti-CD40 antibody treatment of mesothelioma tumors, NK cells help acquire and/or maintain systemic immunity and long-term effector/memory responses." (PMID 36831074, 2023). "Therefore, to address this issue we examined the role of macrophages in young (3 months) vs. elderly (20–24 months) mesothelioma-bearing female C57BL/6J mice during tumor growth and following treatment with intra-tumoral IL-2/anti-CD40 immunotherapy." (PMID 30459812, 2018). "These CAR T cells were expanded for seven days with CD3/CD28 beads and IL-2 in the presence or absence of CAL-101 or AKTi before transfer into mice bearing subcutaneous M108 mesothelioma tumor." (PMID 29033940, 2017). "Although clinical trials in mesothelioma are still limited, preclinical studies in murine models have demonstrated efficacy of CD40 agonists as monotherapy not just in adjuvant settings post-surgery but also in combination with other immunostimulatory agents, such as TLR ligands and IL-2." (PMID 41463268, 2025). "Furthermore, the age-related suppressive status of elderly TDLN CD11c+ cells and T cells was exacerbated during IL-2/CD40 immunotherapy, which may have contributed to its reduced efficacy in elderly mice with mesothelioma." (PMID 30560130, 2018). "Human mesothelioma exosomes were shown to alter the way in which immune cells respond to IL-2 by inhibiting IL-2-driven priming of both cytotoxic NK cells and CD8+ T cells, while leaving the IL-2-dependent activation of the immunosuppressive Treg populations unaffected." (PMID 29696022, 2018).
preeclampsia (20 papers, 2010 to 2025). Preeclampsia is a hypertensive disorder of pregnancy that is characterized by new-onset hypertension with proteinuria presenting after 20 weeks of gestation, and depending on mild or severe forms may initially present with severe headache, visual disturbances, and hyperreflexia. "Due to the increase in the ratio of Th17/Treg cells, IL-2 has also been linked to preeclampsia, miscarriage, and the IL-7/IL-7R signaling pathway in fetal miscarriage." (PMID 38131979, 2023). "Elevated IL-2 concentrations may reflect the proinflammatory environment associated with preeclampsia." (PMID 33680514, 2021). "The extraction process focused on both clinical outcomes, such as the incidence of preeclampsia and related maternal and neonatal complications, and biomarker analyses, including levels of anti-inflammatory markers like 15-epi-lipoxin A4 and IL-2." (PMID 40519374, 2025). "This study reveals increased IL-2 concentration in preeclampsia, decreased IL-2 concentrations in LDA-resistance and differential changes of IL-2 throughout gestation based on aspirin resistance." (PMID 38851168, 2024). "IL-2 concentrations were nominally elevated in preeclampsia relative to subjects with normal pregnancy outcomes in the placebo group (FDR = 0.112; nominal p-value = 0.036)." (PMID 38851168, 2024). "IL-2 and IL-2 receptor maternal serum levels have been demonstrated to be increased in preeclampsia and decreased throughout gestation in healthy pregnancies." (PMID 38851168, 2024). "The results of this study suggest a potential role for IL-2 in the development of preeclampsia modulated by an individual’s response to aspirin." (PMID 38851168, 2024). "After adjusting for preeclampsia, a potential confounder in preterm birth pathophysiology, our observations remained consistent, with notably reduced Flt3L and increased IL-6, IL-2 and IL-10 levels." (PMID 39627409, 2024). "In this study, we observe increased IL-2 concentrations in preeclampsia in placebo and decreased IL-2 concentrations in LDA-resistant individuals exposed to LDA." (PMID 38851168, 2024). "Although this study investigated IL-2, there is still more to understand about preeclampsia and the other factors that contribute to this disease." (PMID 34685775, 2021). "In preeclampsia, the proinflammatory : anti-inflammatory ratio (IL-2: IL-4 and IFN-γ : IL-4) is elevated compared to healthy pregnant controls, reflecting the more proinflammatory response associated with preeclampsia." (PMID 33680514, 2021). "Proinflammatory cytokines (TNF-α, IFN-γ, IL-2, IL-8, and IL-6) are significantly elevated in preeclampsia." (PMID 33680514, 2021). "In conclusion, we have demonstrated that a set of cytokines, IL-22, MDC, and IL-2/IL-4 can be used to diagnose preeclampsia, and what’s more to discriminate from gestational hypertension." (PMID 34248946, 2021). "The in-depth analysis showed that the IL-22, MDC, and IL2/IL-4 ratio can be used to discriminate between preeclampsia, gestation hypertension and healthy pregnancy." (PMID 34248946, 2021). "Using a diagnostic test assessment characteristic parameters (IL-22, MDC/CCL22, IL-2/IL-4 ratio) have been identified and cut-off values have been proposed to diagnose preeclampsia." (PMID 34248946, 2021). "Research using a murine model of placental ischemia in pregnancy proposed that IL-2 is a key cytokine mediating natural killer cell activation and placental health in preeclampsia." (PMID 33680514, 2021). "Maternal serum IL-2 concentrations are significantly higher in preeclampsia compared to healthy pregnant women." (PMID 33680514, 2021). "This is plausible since preeclampsia patients have increased circulating levels of tumor necrosis factor alpha (TNFα), interleukin (IL)-2, IL-6, and IL-17." (PMID 31434191, 2019).
preeclampsia (continued). "These individuals exhibited significantly lower concentrations of IL-2, a biomarker linked to immune modulation, and showed no significant reduction in preeclampsia prevalence compared to placebo (P > 0.05)." (PMID 40519374, 2025). "Regardless of the discrepancies, the analysis of a broad panel of 53 mediators suggests that IL-22, CCL22, and the IL-2/IL-4 ratio may aid in the diagnosis of PE and even in differentiating preeclampsia from gestational hypertension." (PMID 41156157, 2025). "We performed a secondary analysis of a randomized, placebo-controlled trial of LDA (60 mg daily) for preeclampsia prevention in high-risk individuals (N = 524) on pregnancy outcomes and concentrations of PLGF, IL-2, IL-6, thromboxane B2 (TXB2), sTNF-R1 and sTNF-R2 from maternal serum." (PMID 38851168, 2024). "IL-2 is elevated in many chronic inflammatory conditions and is increased during preeclampsia (PE)." (PMID 34685775, 2021). "IL6 is associated with reduced TGFB output and IL2-mediated STAT5 signaling, and is a possible candidate contributing to impaired Treg capacity in preeclampsia, given that elevated expression of IL6 is seen in gestational tissues of women who later develop the condition." (PMID 30984163, 2019). "Mean concentrations of all biomarkers did not significantly differ between LDA resistance groups within individuals that developed preeclampsia, although LDA-sensitive individuals had higher levels of IL-2 compared to those that were LDA-resistant." (PMID 38851168, 2024). "Stimulation of expansion of Tregs with IL-2 and TGF-β1 resulting in decreased Tregs/Th17 ratio along with PD-L1 Fc administration can be a novel therapeutic approach for managing preeclampsia." (PMID 39328700, 2024). "It has been reported that a shift towards Th1-type immunity (increase in IL-2/IL-4 and IFN-γ/IL-4 ratios) in women with preeclampsia." (PMID 33224295, 2019). "The ratios IL-2/IL-10 and TNF-α/IL-10 in maternal serum are higher in preeclampsia than in normal pregnancy." (PMID 26247971, 2015). "Women with preeclampsia were found to exhibit increased concentrations of interleukin (IL)-1, IL-6, and tumor necrosis factor alpha (TNF-α) in their plasma and amniotic fluid, alongside elevated levels of IL-2 and interferon gamma (IFN-γ)." (PMID 41375625, 2025). "IL-2 does not appear to be present at high concentrations in healthy pregnancy but is elevated in women who develop complications including preeclampsia which is discussed in more detail later in this review." (PMID 33680514, 2021). "Possible mechanisms by which dominant Th1 immune responses induce the clinical aspects of preeclampsia are not completely known, but many of the respective Th1 cytokines (TNF-α, IL-2, IL-12, IL-18, and IFN-γ) have been reported to induce apoptosis of trophoblasts." (PMID 30079067, 2018). "It has been recently demonstrated that berberine hydrochloride could alleviate preeclampsia by regulating IL2/IL10 and BCL2/BAX expressions in preeclampsia rat models." (PMID 29765977, 2018). "It has been shown that IL-17-producing lymphocytes are increased in the peripheral blood of preeclamptic patients in the third trimester of pregnancy and a significant correlation has been found between levels of Th17, IL-2-, and IFN-γ-producing T cells and the development of preeclampsia." (PMID 30079067, 2018). "Aspirin has been shown to increase IL-2 production by human peripheral blood lymphocytes, which we observe in LDA-sensitive healthy pregnancies but not those that develop preeclampsia as those have already elevated levels of IL-2." (PMID 38851168, 2024).
acute coronary syndrome (19 papers, 2018 to 2026). Signs and symptoms related to acute ischemia of the myocardium secondary to coronary artery disease. "Compared to stable CAD and healthy subjects, acute coronary syndromes are associated with long-term increases in serum concentrations of anti- and pro-inflammatory cytokines, such as IL-2, IL-10, and TNF." (PMID 38541966, 2024). "The LILACS trial established that low-dose IL-2 is both safe and biologically effective for patients with acute coronary syndrome (ACS) and stable ischemic heart disease." (PMID 41511355, 2025). "The IVORY trial, a randomized, placebo-controlled study, demonstrated that low-dose IL-2 administration in patients with acute coronary syndrome (ACS) resulted in a significant reduction in arterial inflammation, as assessed by 18F-FDG PET/CT imaging." (PMID 41511355, 2025). "The Low-dose InterLeukin 2 (IL-2) in patients with stable ischaemic heart disease and Acute Coronary Syndromes (LILACS) study, established the safety of low-dose IL-2 and its biological efficacy in IHD." (PMID 36207050, 2022). "The Low-dose InterLeukin 2 in patients with stable ischaemic heart disease and Acute Coronary Syndromes (LILACS) was the first study to explore the safety of low dose of IL-2 and its ability to expand Treg cells in this patient cohort." (PMID 36207050, 2022). "The IVORY trial is designed to assess the effects of low-dose IL-2 on vascular inflammation in patients with acute coronary syndromes (ACS)." (PMID 36207050, 2022). "The LILACS trial (Low-dose interleukin-2 in Patients with stable ischemic heart disease and acute coronary syndrome) explored the potential of Treg expansion in patients with acute coronary syndrome, in pursuit of therapeutically targeting Tregs in humans." (PMID 35693830, 2022). "We also assessed the ability of low-dose IL-2 to activate ILC2 in a double-blind randomized clinical trial of patients with acute coronary syndromes (ACS)." (PMID 34503682, 2021). "Activated T-cells secrete IL-2, and their higher count are correlated with acute coronary syndrome (ACS)." (PMID 29337902, 2018). "Low-dose interleukin-2 in patients with stable ischaemic heart disease and acute coronary syndromes is a single-centre, first-in-class, dose-escalation, two-part clinical trial." (PMID 30224390, 2018). "IL-2 efficacy is being further investigated in the context of ACS by the IVORY (Low-dose interleukin 2 for the reduction of vascular inflammation in acute coronary syndromes) trial (NCT04241601), with index vessel inflammatory parameters as assessed by PET-CT scan as the primary endpoint." (PMID 39124834, 2024). "Of note, low-dose IL-2-mediated expansion of Tregs is currently being investigated in a phase I/II clinical trial for prevention of recurrent MI in patients with stable ischemic disease or acute coronary syndromes." (PMID 34485396, 2021). "In the context of acute coronary syndrome (ACS), the administration of low-dose interleukin-2 (IL-2) serves primarily as an immunomodulatory intervention designed to mitigate vascular inflammation through the expansion of regulatory T cells (Tregs)." (PMID 41511355, 2025). "IL-2 was chosen for its high score, high relevance to ILC2 function, and its potential as a therapeutic modulator of immune responses in patients with acute coronary syndrome (ACS)." (PMID 34503682, 2021). "One such CK-CKR pair is the interaction interface between IL2 and IL2RA, which may be targeted for better treatment of Acute Coronary Syndrome." (PMID 38789577, 2024).